USP9X (ubiquitin specific peptidase 9 X-linked)
Diseases named in the same sentence as USP9X in open-access papers (continued):
Sharing a sentence is not in itself a finding about the gene and the disease.
nasopharyngeal carcinoma (1 paper, 2023). A carcinoma arising from the nasopharyngeal epithelium. "USP9X upregulates the expression of ABCB1 and MRP2 by stabilizing β-catenin, thus affecting cisplatin resistance in nasopharyngeal carcinoma (NPC) cells." (PMID 36694209, 2023).
Noonan syndrome (1 paper, 2021). Noonan Syndrome (NS) is characterized by short stature, typical facial dysmorphism and congenital heart defects. "Secondary screening confirmed the enhanced sensitivity of RIT1-mutant cells to depletion of USP9X and AURKA along with the RAS pathway and Noonan syndrome genes SHOC2 and SOS1." (PMID 34373451, 2021).
oropharyngeal squamous cell carcinoma (1 paper, 2021). "From this screening, we have now thoroughly validated that depletion of the ubiquitin-specific protease 9X (USP9X) in HeLa and oropharyngeal squamous cell carcinoma (UMSCC74A) cells using small interfering RNA (siRNA), leads to significantly decreased survival of cells after high-LET radiation." (PMID 34277417, 2021). "Here, we observed that USP9X-depleted HeLa and UMSCC74A oropharyngeal squamous cell carcinoma cells have reduced levels of CEP55 and CEP131." (PMID 34277417, 2021). "To further validate that our observations were specific, we utilized two single siRNA sequences (USP9X_6 and USP9X_8) that were demonstrated to be effective in suppressing USP9X protein levels in both HeLa and UMSCC74A oropharyngeal squamous cell carcinoma cells." (PMID 34277417, 2021).
ovarian adenocarcinoma (1 paper, 2017). An adenocarcinoma that arises from the ovary. "USP9X (p.Met1478Leu) was mutated only in the ovarian adenocarcinoma." (PMID 28103826, 2017).
ovarian disorder (1 paper, 2026). A disease involving the ovary. "Our findings indicate that PAE reduces ovarian reserve through HDAC1-linked epigenetic silencing of Usp9x, exacerbating HIF1α/NOBOX pathway dysfunction, thereby informing aspirin's gestational safety and future interventions for fetal-origin ovarian disorders." (PMID 41524225, 2026).
ovarian tumours (1 paper, 2015). "Exome sequencing identified two novel candidate genes, EIF1AX and USP9X, which are enriched in LGSC compared to SBT, suggesting they may be key contributors to carcinogenesis, although the biological impacts of mutant EIF1AX and USP9X in ovarian tumours remains to be determined." (PMID 26506417, 2015).
renal fibrosis (1 paper, 2018). A final common manifestation of a wide variety of chronic kidney diseases characterized by glomerulosclerosis and tubulointerstitial fibrosis. "In addition, even though WP1130 is an inhibitor of USP9X, administration of WP1130 did not suppress renal fibrosis or Smad4 expression in mice with UUO." (PMID 30114247, 2018).
cancer (100 papers, 2011 to 2026). A tumor composed of atypical neoplastic, often pleomorphic cells that invade other tissues. "This process promotes cancer cell apoptosis and inhibits tumor progression, positioning the USP9X/EGLN3 axis as a promising diagnostic and therapeutic target for CCA." (PMID 41301681, 2025). "The human genome encodes nearly 100 DUBs, many of which—including USP9X—exhibit aberrant expression in cancer." (PMID 41301681, 2025). "The X-linked deubiquitinase USP9X has been implicated in various cellular processes, including cell growth, division, and death, which affect cancer development." (PMID 38474186, 2024). "Elevated USP9X levels have been associated with unfavorable outcomes in patients with GC, indicating its potential as a cancer-promoting factor." (PMID 39605891, 2024). "Studies have shown that MM patients overexpressing USP9X are at higher risk of death and are associated with a poor prognosis of cancer." (PMID 32354135, 2020). "Using these same tools, we compared the combined predictive scores of the USP9X common variants with the female, male and cancer variants." (PMID 33298948, 2020). "In particular, USP9X functions related to mitosis are known to be associated with cancer development and progression." (PMID 31795161, 2019). "Genetic mutations and dysregulations of USP9X expression have been implicated in various human diseases, including neurological disorders and cancers." (PMID 28101374, 2017). "Previous studies have reported USP9X overexpression and mutation in several types of cancer cells, which plays a critical role in tumor progression." (PMID 27517496, 2016). "Various USP9X mutations or copy number variations can be found in 53 of the 86 cancer types (62 %) in cBioPortal for Cancer Genomics." (PMID 27517496, 2016). "Previous data from others and our own group indicated that Usp9X plays a role in the regulation of Mcl-1 and consequently determines susceptibility of cancer cells to the sensitivity of BH3-mimetics." (PMID 26474387, 2015). "Through these roles, USP9X has been found to regulate developmental processes, and deregulated USP9X function is implicated in neurodevelopmental and neurodegenerative diseases as well as various cancers." (PMID 25672900, 2015). "Of the 86 cancer types listed in cBioPortal for Cancer Genomics, mutations or copy number variations in USP9X were found in 53 types (62 %), with the frequency of USP9X within a single cancer type alterations found up to 13 %." (PMID 25672900, 2015). "The discoveries of deleterious USP9X genetic variants found associated with neurological disorders and enriched in cancer samples are in line with the strong selection against USP9X mutation." (PMID 25672900, 2015). "USP9X (ubiquitin-specific peptidase 9X) mutations were identified in 2.6% SBTs and 11% LGSCs, and a focal deletion in a mixed-grade carcinoma." (PMID 26506417, 2015). "In our current analyses, USP9X expression was found to be strongly associated with Mcl-1 expression in the human cancer tissue samples we tested." (PMID 23171055, 2012). "This activity and upregulation of USP9X as well as Mcl-1 have been associated with a poor prognosis and with chemoresistance in a number of cancers." (PMID 23171055, 2012). "Immunoprecipitation (IP) western blotting was employed to further explore the physical interaction between USP9X and Mcl-1 in cancer cells and a strong direct association was observed." (PMID 23171055, 2012). "Notably, protein kinase, DNA-activated, catalytic subunit (PRKDC), and ubiquitin-specific protease 9X (USP9X) had higher mutation frequencies in multiple cancers, mainly including UCEC, SKCM, COAD, and STAD." (PMID 37540295, 2023). "USP9X was increased in HPV-associated cancers, and specifically by 16E6; as such, preserving greater NFX1-123 expression, through augmented USP9X, may be an important function during cancer development and progression." (PMID 33808060, 2021).
cancer (continued). "Usp9x is a marker of “stemness” and is mutated in various neurological disorders and cancers." (PMID 33767158, 2021). "In addition to regulating physiological processes, USP9x activity has been also linked to pathological events, including cancer." (PMID 32560247, 2020). "In addition, we find a strong correlation between USP9X and FBW7 immunohistochemical staining in human CRC and show that reduced USP9X was strongly associated with poor clinical outcome in those cancers." (PMID 29346117, 2018). "USP9X is a deubiquitinating enzyme with many known substrates and functions; it has been linked to cancer but the mechanisms remain unclear." (PMID 28361952, 2017). "Furthermore, dysregulation of USP9X has been linked to both human cancers and neurodegenerative diseases." (PMID 28101374, 2017). "In addition, we demonstrate that two SOX2-associated proteins, MSI2 and Ubiquitin Specific Peptidase 9x (USP9X), which have been recently implicated in the growth of other cancers, are required to support the growth and survival of DAOY cells and two GB tumor cell lines, U87 and U118." (PMID 23667531, 2013). "This explains growth suppression in long-term clonogenic assays in most cancer cell lines, and positions USP9X inhibitors as a new class of selective mitotic poisons." (PMID 41946992, 2026). "Further research is needed to elucidate the molecular mechanisms of USP9X in different cancers, maximizing its potential for clinical translation." (PMID 41301681, 2025). "Overexpression of USP9X in cancer activates multiple important pathways, including the PI3K/AKT, Rho/Rho-associated protein kinase, Notch, NK-κB, and Wnt/β-catenin pathways." (PMID 38612674, 2024). "Among about 90 DUBs, USP9X plays diverse roles in different cancers by regulating the stability of its targets." (PMID 39075342, 2024). "USP9X is involved in the tumorigenesis of various types of cancers, and high expression of USP9X is found and associated with poor prognosis of GC." (PMID 39075342, 2024). "We show that USP9x is elevated in human cancer tissues and its suppression impairs NSCLC growth in vitro and in vivo." (PMID 39075050, 2024). "USP9X reportedly enhances cancer cell survival and reduces cell responsiveness to chemotherapy by deubiquitinating and stabilizing YAP." (PMID 39605891, 2024). "USP9X controls tumorous functions such as cell adhesion, cell polarity, cell death and inflammatory processes in cancer cells." (PMID 37658402, 2023). "For example, one of the protooncogenic functions of USP9X stems from its interaction with the anti-apoptotic protein Mcl-1, which promotes the increased expression of Mcl-1 in cancer tissues and inhibits apoptosis 31,32." (PMID 37057289, 2023). "For example, USP9X can control the monoubiquitination of SMAD4 to regulate TGF-β-mediated cancer metastasis." (PMID 35924159, 2022). "USP9X is involved in cancer initiation and development, and intriguingly, its role in cancer has both pro-oncogenic and tumor suppressor functions, likely depending on tissue context." (PMID 36123603, 2022). "USP9X is a ubiquitin protease that has recently been proven to have an important role in cancer development." (PMID 34856948, 2021). "Accumulating evidence demonstrates that USP9X involves in tumorigenesis and chemoresistance in some types of human cancer, such as breast and lung cancer, melanoma, lymphoma, and glioblastoma." (PMID 34112167, 2021). "Recently, more DUBs, such as ubiquitin-specific peptidase 9 X-linked (USP9X), USP22, and OTU domain ubiquitin aldehyde binding 1 (OTUB1), were found to deubiquitinate and stabilize PD-L1 in different cancers." (PMID 34829931, 2021). "USP9X is a DUB that stabilizes the oncogenic MCL-1 in cancer cells and was shown to be overexpressed in MM." (PMID 34203106, 2021). "Ubiquitin-specific peptidase 9X (USP9X) is a ubiquitin protease that has recently been proven to play an important role in cancer development." (PMID 34856948, 2021).
cancer (continued). "While the mechanism of overexpression of MCL1 in cancer is not completely understood, USP9X is thought to stabilize MCL1 by removing degradative Lys-48–linked polyubiquitin chains." (PMID 32354135, 2020). "The role of USP9x in cancer development is quite complex as it can act as both a tumor suppressor and an oncogene." (PMID 32560247, 2020). "Previous studies showed that the function of USP9X in regulating cancer cells is complex and diverse." (PMID 32850399, 2020). "Thus structural modelling of the all likely pathogenic USP9X-female variants located in the catalytic domain provides rationale for disrupted catalytic activity and/or ubiquitin binding, and is supported by analogous mechanisms of several proximal predicted deleterious variants arising in cancer." (PMID 33298948, 2020). "Increased DVL2 ubiquitination activates the PCP pathway via localization to actin-rich projections, making USP9X an important therapeutic target for cancers." (PMID 32549302, 2020). "In vivo studies on cancer mouse model are also indicative for a tumor suppressor role of USP9x in SCC." (PMID 32560247, 2020). "Role of USP9X in cancer is tissue specific and USP9X displays both oncogenic and tumor suppressor activities." (PMID 30911287, 2019). "In this study, we report that the ubiquitin‐specific protease 9X (USP9X) is a bona fide deubiquitinase for BRCA1 in human cancer cells." (PMID 31512408, 2019). "Collectively, these results establish USP9X as a deubiquitinase for BRCA1 and reveal a previously unrecognized role of USP9X in the regulation of HR repair and the sensitivity of cancer cells to DNA‐damaging agents." (PMID 31512408, 2019). "Our study provides the evidence that inhibition of USP9X by WP1130 induces miR-708-mediated c-FLIP suppression in cancer cells." (PMID 30862047, 2019). "We identified a recurrent up-regulation of CDKN1C expression at the mRNA level in different cancer cell types silenced for ZBTB38 or its deubiquitinase USP9X." (PMID 30310057, 2018). "The positive regulation of FBW7 by USP9X reinforces the importance of protein turnover and regulation in tissue homeostasis and cancer." (PMID 29346117, 2018). "USP9X expression has been found to be reduced in several types of human cancer, such as pancreatic, and in kidney tumors and breast cancer cell lines." (PMID 29673168, 2018). "This work also provides a rationale for targeting USP9X when it is expressed in cancer cells with high levels of CIN." (PMID 29669289, 2018). "In two specific OSCC databases, the level of USP9X in cancer was also higher than that in normal tissues." (PMID 29992764, 2018). "It is well established that Usp9X plays a pivotal role in various malignant tumors affecting the nervous system, including GBM6,11,20." (PMID 30478285, 2018). "Both knockdown and chemical inhibition of USP9X have been shown to efficiently promote cancer cell apoptosis." (PMID 28101374, 2017). "We believe that the link between CEP131 and USP9X is one of multiple pathways that appear to act in cancer cells." (PMID 28361952, 2017). "Identification of TDRD3 as a regulator of USP9X is important because it provides an alternative pathway to target MCL-1 in cancer." (PMID 28101374, 2017). "Consistent with the reduction in HIF-2α protein levels, the cell proliferation assay showed that knockdown of USP9X retards the growth rate of cancer cell lines HepG2 and PC3." (PMID 27517496, 2016). "At the same time, analysis of a cohort of cancer patients demonstrated a positive correlation between USP9X and cancer." (PMID 27517496, 2016). "USP9x transcript levels were significantly lower in several cancers compared with normal controls, including breast, thyroid, prostate, liver hepatocellular carcinoma, kidney papillary and ccRCC." (PMID 27462448, 2016). "USP9X is a deubiquitinase that plays important roles in development of the nervous system and in cancer progression." (PMID 27517496, 2016).
cancer (continued). "Since pVHL is a critical tumor suppressor and plays important roles in anaerobic metabolism and cell proliferation, we investigated the effects of USP9X on cancer progression." (PMID 27517496, 2016). "In this study, knockdown of USP9X or treatment with USP9X inhibitor retarded cell growth in cancer cell lines and suppressed tumorigenesis in xenograft models, verifying the oncogenic role of USP9X." (PMID 27517496, 2016). "It seems likely that the relationship between USP9x levels and clinical outcome in different cancers will reflect the balance of its activity on multiple pathways." (PMID 27462448, 2016). "It is likely that the majority of USP9X related cellular activities in cancer are as yet undiscovered, and to address the complexities of these mechanisms will be challenging." (PMID 27517496, 2016). "Overall, the evidence suggests that the role of USP9X in cancer is tissue specific and implicates USP9X as a clinically relevant candidate warranting further investigation." (PMID 25672900, 2015). "USP9X alterations are even more frequent in other cancers; for example, it was found in 22 % of gingivo-buccal oral squamous cell carcinoma (OSCC-GB) samples." (PMID 25672900, 2015). "A comprehensive in situ hybridisation analysis of nine human cancers revealed that several DUBs, including USP9X, are frequently dysregulated in cancers." (PMID 25672900, 2015). "Ongoing large-scale cancer sequencing projects are predicted to reveal further genetic evidence of the involvement of USP9X in cancer." (PMID 25672900, 2015). "One oncogenic function of USP9X derives from its interaction with the anti-apoptopic protein MCL1, which is highly expressed in cancers and associated with resistance to chemotherapy." (PMID 25672900, 2015). "In these models, genetic inactivation of Usp9x (either by insertional mutagenesis or Pdx1-Cre mediated deletion) was found to enhance oncogenic KrasG12D in accelerating tumourogenesis and cancer progression." (PMID 25672900, 2015). "In line with these roles, recent investigations of neurodevelopmental and neurodegenerative disorders as well as cancer have revealed the involvement of USP9X." (PMID 25672900, 2015). "Our follow-up studies indicated that the ability of miR-26b to inhibit cancer cell invasion was mediated through its ability to downregulate USP9X expression." (PMID 24890815, 2014). "It has been demonstrated in this regard that a reduction in the Mcl-1 levels in WP1130-treated cancer cells parallels the inhibition of USP9X activity." (PMID 23171055, 2012). "Our current analyses demonstrate in principle that the expression of USP9X, Mcl-1 and Bcl-xL contributes to chemoresistance in cancer cells." (PMID 23171055, 2012). "In cancer, USP9X is found as an oncogene or as a tumour suppressor depending on context, and its utility as a target for cancer therapy remains unclear." (PMID 41946992, 2026). "Intriguingly, USP9X plays a context-dependent role across cancer types and stages." (PMID 41301681, 2025). "Therefore, the mutual positive regulatory relationship between USP9X and TGF-β signaling occurs through various physiological and pathological processes, which makes USP9X an appropriate target of TGF-β signaling in HGSOC or other cancers." (PMID 40246814, 2025). "USP9X, a key member of the deubiquitinase family, exhibits complex and diverse regulatory functions in tumor development, demonstrating a remarkable dual role—either promoting or suppressing cancer—depending on the tumor type and specific molecular context." (PMID 41301681, 2025). "Also, additive antitumor activity has been observed with gemcitabine and ABT‐737 in various cancers, where their combined effect disrupts the interaction between USP9X and Mcl‐1, enhancing apoptosis and potentially overcoming inherent drug resistance." (PMID 40405831, 2025). "As a result, USP9x activity allows to maintain proline cycling in cancer cells." (PMID 39075050, 2024).